UBE2T (ubiquitin conjugating enzyme E2 T)
Diseases named in the same sentence as UBE2T in open-access papers (continued):
Sharing a sentence is not in itself a finding about the gene and the disease.
multiple myeloma (6 papers, 2019 to 2025). "Several studies have reported that the ubiquitin-conjugating enzyme E2 T (UBE2T) is overexpressed in multiple myeloma (MM)." (PMID 40259951, 2025). "The expression of UBE2T increases with the progression of multiple myeloma, especially in the early stage." (PMID 33937050, 2021). "The oncogenic contribution of UBE2T has been manifested in a wide spectrum of cancers from solid tumors to multiple myeloma." (PMID 34461934, 2021). "Besides its relevance in FA, accumulating evidence indicates that UBE2T also plays an oncogenic role in various cancer, including hepatocellular carcinoma, gastric cancer, breast cancer, multiple myeloma, osteosarcoma, and NSCLC." (PMID 34461934, 2021). "Besides solid tumors, the linkage between high UBE2T and poor survival has been recently reported in multiple myeloma." (PMID 34257599, 2021). "This justify both genes UBE2T and UBE2O, and their respective protein expressions, being associated with several cancers and diseases, such as hepatocellular carcinoma, multiple myeloma (MM), bladder, gastric cancer, multiple myeloma, breast and prostate cancer, and mixed-lineage leukemia." (PMID 37373211, 2023).
gallbladder cancer (5 papers, 2020 to 2023). "UBE2T overexpression is reported to lead to unfavorable prognosis in patients with gallbladder cancer and UBE2T can be used as an independent prognostic biomarker for patients with gallbladder cancer." (PMID 33934686, 2021). "By analyzing microarray data, UBE2T was considered a hub gene in patients with gallbladder cancer, and it might serve as a biomarker for gallbladder cancer." (PMID 35035504, 2022).
nasopharyngeal carcinoma (5 papers, 2016 to 2022). A carcinoma arising from the nasopharyngeal epithelium. "Elevated expression of UBE2T is also associated with lung, gastric, prostate, and nasopharyngeal cancer." (PMID 27729585, 2016). "UBE2T enhances nasopharyngeal carcinoma cell multiplication and invasion by activating the AKT/GSK3β/β-catenin pathway." (PMID 33934686, 2021). "Strikingly, UBE2T has been verified to be an independent prognostic factor for nasopharyngeal carcinoma." (PMID 31128423, 2019). "verified that UBE2T elevated the colony formation and proliferation of nasopharyngeal carcinoma cells both in vitro and in vivo, which is in line with our findings that the silencing of UBE2T could diminish the LCSCs’ sphere and colony formation and proliferation abilities." (PMID 31128423, 2019). "Finally, it was demonstrated that UBE2T is highly expressed in nasopharyngeal carcinomas." (PMID 27729585, 2016). "Interestingly, elevated UBE2T expression in nasopharyngeal carcinomas activates the AKT/GSK3β/β-catenin pathway, and inhibition of the pathway with the AKT inhibitor MK-2206 2HCL blocks the pro-metastatic effect of UBE2T in nasopharyngeal cancers cells." (PMID 27729585, 2016). "Increasing evidence has shown that UBE2T plays an important role in genomic integrity and carcinogenesis; however, its role in nasopharyngeal carcinoma (NPC) has not been investigated." (PMID 26943030, 2016).
ovarian carcinoma (5 papers, 2015 to 2024). A malignant neoplasm originating from the surface ovarian epithelium. "The present study was the first to demonstrate that the expression of UBE2T is higher in ovarian cancer cells with a BRCA gene mutation." (PMID 36088429, 2022). "The survival analysis of all epithelial ovarian cancer samples included in the GSE51088 dataset demonstrated that the high expression of the UBE2T gene was associated with poor prognosis." (PMID 36088429, 2022). "This is the first study to demonstrate that UBE2T expression is higher in ovarian cancer with BRCA mutation." (PMID 36088429, 2022). "The analysis demonstrated that the expression levels of UBE2T were higher in ovarian cancer cells with a BRCA gene mutation." (PMID 36088429, 2022). "The expression of UBE2T is significantly increased in ovarian cancer cells with a BRCA mutation." (PMID 36088429, 2022). "Moreover, we investigated the difference in UBE2T expression in ovarian cancer tissues with different BRCA mutations." (PMID 36088429, 2022). "UBE2T expression was higher in ovarian cancer tissue with BRCA mutations." (PMID 36088429, 2022). "Ubiquitin-binding enzyme E2T (UBE2T), a member of the E2 family of the ubiquitin–proteasome pathway, is associated with tumorigenesis of varioustumours; however, its role and mechanism in ovarian cancer remain unclear." (PMID 36088429, 2022). "We designed three siRNAs that can silence UBE2T and transfected them into ovarian cancer cell lines SKOV3 and HO8910." (PMID 36088429, 2022). "We investigated the expression of UBE2T in ovarian cancer and normal ovarian tissues by immunohistochemistry." (PMID 36088429, 2022). "In other words, in vivo experiments in mice demonstrated that UBE2T promotes EMT in ovarian cancer cells." (PMID 36088429, 2022). "The results showed a significant correlation between UBE2T and the expression of these genes in ovarian cancer." (PMID 36088429, 2022). "The findings demonstrated that UBE2T was highly expressed in ovarian cancer tissues with BRCA mut versus those with BRCA wnt (74.3% and 34.3%, respectively); this difference was statistically significant." (PMID 36088429, 2022). "Taken together, the findings suggested that UBE2T promotes the occurrence and development of ovarian cancer by promoting EMT in cancerous cells." (PMID 36088429, 2022). "The results showed that the expression of UBE2T protein in five ovarian cancer cell lines (i.e. CAOV3, SKOV3, ES2, HO8910 and A2780) was significantly higher than that measured in a normal ovarian epithelial cell line (IOSE80)." (PMID 36088429, 2022). "In this study, we found that the PI3K-AKT pathway and the proliferative and invasive ability of ovarian cancer cells were significantly inhibited following UBE2T silencing in ovarian cancer cell lines." (PMID 36088429, 2022). "Subsequently, immunohistochemistry was used to verify the high expression of UBE2T in ovarian cancer." (PMID 36088429, 2022). "This study found that the proliferation and invasion of ovarian cancer cells were significantly inhibited after UBE2T silencing." (PMID 36088429, 2022). "In this study, bioinformatic analysis revealed that UBE2T was highly expressed in ovarian cancer, and this high expression was closely related to the poor prognosis of patients." (PMID 36088429, 2022). "UBE2T was highly expressed in ovarian cancer tissues compared with normal ovarian tissues (54.3% and 25.5%, respectively); this difference was statistically significant." (PMID 36088429, 2022). "In this study, we found that the expression of UBE2T was significantly increased in ovarian cancer cell lines and tissues." (PMID 36088429, 2022). "The findings also suggested that the depletion of UBE2T inhibits the invasion of ovarian cancer cells via inhibition of the PI3K-AKT pathway." (PMID 36088429, 2022).
ovarian carcinoma (continued). "The results showed that the mRNA expression levels of the UBE2T gene in the five ovarian cancer cell lines (i.e. CAOV3, SKOV3, ES2, HO8910 and A2780) were significantly higher than those recorded in the normal ovarian epithelial cell line (IOSE80)." (PMID 36088429, 2022). "This study shows that UBE2T plays a carcinogenic role in ovarian cancer by regulating EMT through the PI3K-AKT pathway." (PMID 36088429, 2022). "Our study revealed that UBE2T is highly expressed in ovarian cancer; this high expression was closely related to poor prognosis." (PMID 36088429, 2022). "The results demonstrated that UBE2T promotes the invasion of ovarian cancer cells, and UBE2T knockout significantly inhibits the invasion of these cells." (PMID 36088429, 2022). "Collectively, these findings indicated that UBE2T promotes the proliferation and invasion of ovarian cancer cells via the PI3K-AKT pathway." (PMID 36088429, 2022). "In this study, we analysed the expression of UBE2T in ovarian cancer and analysed the specific mechanism through which it regulates cell proliferation." (PMID 36088429, 2022). "In ovarian cancer, UBE2T may influence the epithelial–mesenchymal transition (EMT) via mTOR targets within the PI3K-AKT pathway." (PMID 39791716, 2024). "Moreover, we demonstrated that UBE2T gene silencing significantly inhibited ovarian cancer cell proliferation and invasion." (PMID 36088429, 2022). "Immunohistochemistry was used to validate the high expression of UBE2T in ovarian cancer." (PMID 36088429, 2022). "RT-PCR assay was used to analyse the expression levels of UBE2T mRNA in ovarian cancer cell lines." (PMID 36088429, 2022). "UBE2T may regulate the EMT process of ovarian cancer cells through mTOR targets in PI3K-AKT pathway." (PMID 36088429, 2022). "This suggests that UBE2T can affect ovarian cancer cell function by regulating EMT occurrence." (PMID 36088429, 2022). "However, the expression levels, mechanism and clinical significance of UBE2T in ovarian cancer are unclear." (PMID 36088429, 2022). "The present findings suggest that UBE2T may be a valuable new marker for the early diagnosis and prognosis of ovarian cancer." (PMID 36088429, 2022). "We studied the protein expression of UBE2T in ovarian cancer cell lines using western blotting." (PMID 36088429, 2022). "UBE2T may promote the progression of ovarian cancer by promoting the occurrence of EMT in ovarian cancer cells." (PMID 36088429, 2022). "This suggested that UBE2T promotes the proliferation of ovarian cancer cells." (PMID 36088429, 2022). "This suggests that UBE2T may promote the proliferation, invasion and metastasis of ovarian cancer by promoting EMT in cancerous cells." (PMID 36088429, 2022). "This shows that UBE2T silencing inhibits EMT of ovarian cancer cells." (PMID 36088429, 2022). "We noticed that the gene UBE2T was significantly upregulated in ovarian cancer tissues." (PMID 36088429, 2022). "We hypothesised that UBE2T regulates the invasive ability of ovarian cancer cells by regulating their EMT via the PI3K-AKT pathway." (PMID 36088429, 2022). "In addition, we also observed that the growth of ovarian cancer tumours on the body surface of mice was significantly inhibited after the silencing of UBE2T in SCID mice." (PMID 36088429, 2022). "Moreover, the downregulation of UBE2T expression could inhibit the proliferation of ovarian cancer cells." (PMID 36088429, 2022). "Moreover, it was found that UBE2T may influence the occurrence and development of ovarian cancer by affecting tumour cell proliferation and invasion, intercellular adhesion, and extracellular matrix decomposition and synthesis." (PMID 36088429, 2022). "Hence, UBE2T may be a valuable novel biomarker for the early diagnosis and prognosis and treatment of ovarian cancer." (PMID 36088429, 2022). "Also, UBE2T may promote the proliferation and invasion of ovarian cancer cells through the PI3K-AKT pathway." (PMID 36088429, 2022).
ovarian carcinoma (continued). "Further, UBE2T inhibition may be effective for treating ovarian cancer." (PMID 36088429, 2022). "Furthermore, the inhibition of UBE2T may be a new target for the treatment of ovarian cancer." (PMID 36088429, 2022). "The Transwell assay showed that the invasive ability of ovarian cancer cells (SKOV3 and HO8910) was significantly decreased after UBE2T silencing." (PMID 36088429, 2022). "This suggests an interaction between the UBE2T and BRCA genes, which affects the occurrence and development of ovarian cancer." (PMID 36088429, 2022). "Therefore, UBE2T may promote the occurrence and development of ovarian cancer by promoting EMT." (PMID 36088429, 2022). "Moreover, UBE2T may interact with BRCA to affect ovarian cancer occurrence and development." (PMID 36088429, 2022). "This study demonstrated that UBE2T regulates EMT via the PI3K-AKT pathway and plays a carcinogenic role in ovarian cancer." (PMID 36088429, 2022). "Following inhibition of UBE2T, the surface phenotype of ovarian cancer cells changes from the stromal phenotype to the epithelial phenotype, indicating that EMT is inhibited in ovarian cancer cells." (PMID 36088429, 2022). "Nevertheless, future research on UBE2T and BRCA may offer more beneficial treatment options to patients with ovarian cancer." (PMID 36088429, 2022). "However, the role of UBE2T in ovarian cancer has not been specifically reported." (PMID 36088429, 2022).
glioma (4 papers, 2020 to 2026). A benign or malignant brain and spinal cord tumor that arises from glial cells (astrocytes, oligodendrocytes, ependymal cells). "Bioinformatics analysis identified UBE2T as an independent risk factor for gliomas." (PMID 32491994, 2020). "Collectively, these findings uncover a previously unrecognised MAPK/ERK‐UBE2T‐FA axis in glioma and highlight BA as a potential adjuvant to overcome cisplatin resistance through transcriptional repression of UBE2T." (PMID 41486508, 2026). "Western blot analysis demonstrated that BA differentially affected multiple signalling pathways regulating UBE2T expression in glioma cells." (PMID 41486508, 2026). "Taken together, these results demonstrated that BA inhibited MAPK/ERK signalling, thereby lowering UBE2T levels, preventing FA pathway activation, and ultimately enhancing the cytotoxic response of glioma tumours to cisplatin in vivo." (PMID 41486508, 2026). "Among these, only UBE2T exhibited a pronounced reduction in protein abundance when glioma cells were pretreated with BA prior to cisplatin exposure." (PMID 41486508, 2026). "In conclusion, our study delineates a mechanistic axis wherein MAPK/ERK signalling transcriptionally sustains UBE2T expression and FA pathway activation, conferring platinum resistance in glioma." (PMID 41486508, 2026). "The analysis revealed that UBE2T expression is an independent prognostic biomarker for patients with glioma." (PMID 32491994, 2020). "Given that BA has previously been implicated in blocking diverse canonical YY1/FAS, ERβ, insulin/IGF‐1, MAPK/ERK and Notch signalling pathways in different pathological models, we next investigated which pathway was responsible for UBE2T downregulation in glioma." (PMID 41486508, 2026). "Since previous study has shown that UBE2T interacted with GRP78 and promoted glioma cell migration and invasion, we hypothesized that UBE2T may function as an oncogene in cervical cancer through GRP78/FAK pathway in this study." (PMID 34703898, 2021). "Additionally, neither cycloheximide (CHX) nor the proteasome inhibitor MG132 altered UBE2T protein levels in BA‐treated glioma cells, thereby ruling out protein degradation." (PMID 41486508, 2026).
anemia (3 papers, 2021 to 2025). A reduction in the number of red blood cells, the amount of hemoglobin, and/or the volume of packed red blood cells. "UBE2T is a criticalE2 enzyme involved in the anemia pathway’s DNA repair, and its mediatedubiquitination regulates multiple cancer-related pathways." (PMID 40521894, 2025). "UBE2T engage in the DNA repair pathway through catalyzing the Fanconi Anemia Complex monoubiquitination." (PMID 33313822, 2021). "Also in the signature were genes encoding the DNA glycosylase NEIL3, Fanconi Anemia factors (FANCD2, UBE2T), the ubiquitin protein ligase UBE3B, and two specialized DNA polymerases, POLM and POLQ, involved in the non-homologous end-joining (NHEJ) pathways of DSB repair." (PMID 34067180, 2021).
breast tumors (3 papers, 2017 to 2021). "Significantly increased mRNA levels were found in breast tumors compared to healthy controls for UBE2T, UBE2C, BIRC5, TCEB2." (PMID 33671201, 2021). "Just like the CST2, GJB2, UBE2T, NUF2 and ORC6 also showed the same high expression level in breast tumors." (PMID 31182966, 2019). "Furthermore, we found that UBE2T and DTL were amplified in around 12% of breast tumors based on data contained at cBioportal." (PMID 29235520, 2017).
cervical cancer (3 papers, 2021 to 2024). A primary or metastatic malignant neoplasm involving the cervix. "The correlation between UBE2T and the clinical characteristics of patients with cervical cancer should be investigated to validate the diagnostic or prognostic roles in the future." (PMID 34703898, 2021). "Suppression of GRP78/FAK activation was implicated in the suppressive effect of UBE2T silencing on cervical cancer." (PMID 34703898, 2021). "The effect of UBE2T on self-renewal capacity of cervical cancer cell was assessed through tumorsphere formation assay." (PMID 34703898, 2021). "Collectively, UBE2T promoted cervical cancer stem cell traits and exerted an oncogenic role through activation of the GRP78/FAK pathway." (PMID 34703898, 2021). "Since UBE2T has been shown to be involved in the maintenance of chromosome stability and cell proliferation, thereby indicating the oncogenic nature in various tumors, the role of UBE2T in cervical cancer was then investigated in this study." (PMID 34703898, 2021). "In this study, our results first showed that the expression of UBE2T was higher in both of cervical cancer tissues and cells than that in the normal tissues and cells." (PMID 34703898, 2021). "Decreased cell viability in HeLa induced by silencing of UBE2T was also restored by overexpression of GRP78 (Figure A1), demonstrating that UBE2T contributed to cervical cancer cell growth and metastasis through GRP78/FAK activation." (PMID 34703898, 2021). "Microarray analysis based on GEPIA (Gene Expression Profiling Interactive Analysis) database showed that UBE2T was upregulated in the cervical cancer tissues (n = 306) compared to the normal tissues (n = 13)." (PMID 34703898, 2021). "The oncogenic role of UBE2T in cervical cancer was then confirmed by the functions assays in this study." (PMID 34703898, 2021). "In summary, UBE2T promoted the growth and metastasis of cervical cancer and facilitated the maintaining of the stem cell-like features in cervical cancer." (PMID 34703898, 2021). "The effect of UBE2T on epithelial-mesenchymal transition of cervical cancer cells should be investigated in further researches." (PMID 34703898, 2021). "Western blotting assay also identified the upregulation of UBE2T in the tumor tissues and cervical cancer cell lines." (PMID 34703898, 2021). "The stem cell-related transcription factors, including SOX2, Oct4, and Nanog, were decreased in UBE2T-silenced cells and increased in UBE2T-overexpressed cells, revealing that cervical cancer stem cell traits were promoted by UBE2T." (PMID 34703898, 2021). "Knockdown of UBE2T reduced cervical cancer cell viability and suppressed the proliferation, invasion, and migration." (PMID 34703898, 2021). "Additionally, UBE2T overexpression in cervical cancer cells enhances self-renewal capacity, indicating its role in promoting cervical cancer stem cell traits." (PMID 39791716, 2024). "The stem cell-related transcription factors, including SOX2, Oct4, and Nanog, were decreased in UBE2T-silenced HeLa cells in this study, suggesting that knockdown of UBE2T might suppress the stem cell-like features in cervical cancer." (PMID 34703898, 2021). "Moreover, mRNA expression of UBE2T was also upregulated in the cervical cancer tissues compared with normal tissues." (PMID 34703898, 2021). "Higher expression of UBE2T in cervical cancer tissues and cells was first identified in this study." (PMID 34703898, 2021). "Therefore, results in this study indicated that UBE2T contributed to cervical cancer cell growth through activation of GRP78/FAK pathway." (PMID 34703898, 2021). "Moreover, UBE2T overexpression cervical cancer cells demonstrated enhanced self-renewal capacity with upregulation of SOX2, Oct-4, and Nanog protein." (PMID 34703898, 2021). "Moreover, the cervical cancer cell growth and metastasis were suppressed by knockdown of UBE2T." (PMID 34703898, 2021).